CCL5 (C-C motif chemokine ligand 5)
Diseases named in the same sentence as CCL5 in open-access papers (continued):
Sharing a sentence is not in itself a finding about the gene and the disease.
psoriasis (30 papers, 2010 to 2025). An autoimmune condition characterized by red, well-delineated plaques with silvery scales that are usually on the extensor surfaces and scalp. "The Th17 chemokine CXCL8 was secreted to a higher amount by psoriasis-derived T cells (3.5 versus 2.3 ng/ml, p = 0.72), while the Th2-associated chemokine CCL-5 was released more by ACD T cells (4.5 versus 0.9 ng/ml, p = 0.53)." (PMID 25058585, 2014). "CCL5 has been found to be associated with various cell-mediated hypersensitive disorders such as psoriasis, atopic dermatitis and irritant contact dermatitis." (PMID 20090949, 2010). "Chemokines, including CCL3 and CCL5, participate in the pathogenesis of psoriasis by recruiting and activating T cells, macrophages, and neutrophils." (PMID 37111171, 2023). "CCL5 has been implicated in the progression of scleroderma, while IL-1β and CXCL10 have been proposed as biomarkers of disease progression in psoriasis." (PMID 37228128, 2023). "The serum level of CCL5/RANTES was significantly higher in patients with the psoriasis area and severity index (PASI) ≥ 15 (p = 0.01)." (PMID 36362116, 2022). "Connection between PRINS and psoriasis has been described in several earlier studies; for example, through the regulation of certain inflammatory mediators (IL-6 and CCL5) by PRINS in nucleic-acid-induced inflammatory reactions." (PMID 35008970, 2022). "Additionally, HDBECs cultured with IL-17, TNFα, and IFNγ, three cytokines heavily implicated in psoriasis pathogenesis, resulted in upregulation of IL-8, CXCL1, CXCL10, and CCL5." (PMID 25369198, 2014). "Additionally, expression of CCL2 mRNA was significantly induced, and there were mild (but not statistically significant) increases in CXCL1, CXCL10, CCL5, and IL-8 in psoriasis-associated mutant CARD14 transfected HDBECs compared to wild-type HDBECs." (PMID 25369198, 2014). "The heatmap showed that C–C motif chemokine ligands (Ccl3, Ccl4, Ccl5, Ccl17, Ccl19-Ps2, and Ccl22) were expressed at higher levels in IMQ-induced psoriasis." (PMID 38566145, 2024). "These include proinflammatory chemokines common to AD and psoriasis, namely CCL2, CCL5 and CCL7, that mediate recruitment of monocytes, T cells, and eosinophils." (PMID 28530223, 2017). "Our data suggest that STAT2 plays a role in the psoriasis pathogenesis by regulating the expression of CXCL11 and CCL5, and thereby attracting IFNγ-producing immune cells to the skin." (PMID 28472186, 2017). "In this respect, chemokine axis such as SDF-1/CXCR4 or CCL5/RANTES are reported to be potent chemo-attractants of proinflammatory immune cells and increased angiogenesis in inflamed skin tissues, such as chronic spontaneous urticaria and psoriasis." (PMID 39104520, 2024). "RANTES/CCL5 is predominantly chemotactic and activates T-cells in chronic inflammatory conditions, including cutaneous diseases such as atopic dermatitis and psoriasis." (PMID 37513335, 2023). "It is therefore tempting to speculate that STAT2 plays a role in the pathogenesis of psoriasis by specifically recruiting Th1 cells to the inflammatory site through its regulation of CXCL11 and CCL5." (PMID 28472186, 2017). "Indeed, LS skin contained significantly more CCL2, CCL5, and CXCL1 compared to NL skin, in both classical psoriasis and the GEN001 patient." (PMID 25369198, 2014). "An increased cebpb expression, epidermal thickness, infiltration of dendritic cells, and γδ T cells as well as the expression of pro-inflammatory cytokines (IL-6, IL-23, and IL-17) and chemokines (CCL5 and CXCL10) could have contributed to this increase in psoriasis severity." (PMID 35663991, 2022). "In psoriasis, estrogen might exert its functions by modulating the expression of certain genes like sex-biased transcription co-factor vestigial-like protein 3 (Vgll3) and CCAAT enhancer binding protein beta (cebpb), microRNAs (miR146a, 21 and 210), and chemokines (CCL5 and CXCL10)." (PMID 35663991, 2022).
psoriasis (continued). "We confirmed that endogenous TWEAK was required for maximal expression of CCL2, CCL5 and CCL7, and furthermore, we found defective production of CCL17 and CCL20 in mice lacking TWEAK in the AD model and the psoriasis model, respectively." (PMID 28530223, 2017).
Thrombocytopenia (27 papers, 2007 to 2024). A reduction in the number of circulating thrombocytes. "CCL5 is a chemokine involved in the generation of inflammatory cellular infiltrates and its low levels are linked to cerebral malaria and severe malarial anaemia, maybe as consequence of thrombocytopaenia and the influence of haemozoin production." (PMID 23433077, 2013). "RANTES (CCL5) levels were significantly decreased in patients, demonstrating severe thrombocytopenia (median 20,767 pg/mL compared to 40,056 pg/mL), while IL-18 levels were significantly increased in these patients (677.9 vs. 448.1 pg/mL)." (PMID 35891358, 2022). "CCL5 levels ≤ cut-off was associated with any grade hand-foot skin reaction (HFSR) (P = 0.025) and thrombocytopenia (P = 0.013)." (PMID 27166185, 2016). "Serum CCL5 levels ≤ cut-off were associated with any grade of HFSR (Odds ratio 9.1, P = 0.025), and of thrombocytopenia (Odds ratio 4.156, P = 0.013), and a trend toward T-BIL increase ≥ grade 2." (PMID 27166185, 2016). "In addition, regorafenib-related toxicities such as HFSR, hyperbilirubinemia, and thrombocytopenia also correlated with CCL5." (PMID 27166185, 2016). "The AnxA1 mimetic significantly reduced thrombocytopenia and haemoconcentration in response to DENV infection and displayed efficacy on controlling innate immunity mediators, with more significant effects in spleen values rather than plasma levels for CCL5 and IL-6." (PMID 35293862, 2022).
atopic dermatitis (26 papers, 2006 to 2025). "This aligns with previous studies demonstrating that IL-37b can inhibit the in vitro induction of pro-inflammatory cytokines (IL-6 and TNF-α) and chemokines (CXCL8, CCL2, and CCL5) related to atopic dermatitis." (PMID 40444012, 2025). "Atopic dermatitis is caused by chronic inflammation of the skin tissue, and the onset of atopic dermatitis is closely related to various inflammatory mediators such as IL-4, IL-13, CCL5, CCL17, and CCL22." (PMID 39599592, 2024). "Other chemokines such as TARC/CCL17, MDC/CCL22, and RANTES/CCL5 are typical Th2 cell-secreted chemokines predominantly expressed by keratinocytes involved in atopic dermatitis." (PMID 34073317, 2021). "In this study, we investigated the molecular mechanism underlying the chrysin-induced suppression of C-C motif chemokine ligand 5 (CCL5) gene expression in atopic dermatitis (AD)-like inflammatory microenvironment." (PMID 33027922, 2020). "Atopic dermatitis increased the expression levels of IL-5, IL-17, chemokine (C-C motif) ligand 5 (CCL5), MIP-1ß, and MIP-2 in the serum of BALB/c mouse." (PMID 30459600, 2018). "Under inflammatory conditions, keratinocytes produce large amount of CCL-5 to attract antigen-presenting cells and T-cells into the epidermis; moreover, CCL-5 is overexpressed in atopic dermatitis and psoriatic lesions." (PMID 28900430, 2017). "We showed that elevated expression of AQP3 led to a reduced expression of differentiation markers, filaggrin in particular and an increased expression of CCL5 and TNFα, two of the most prominent cytokines in atopic dermatitis." (PMID 24260356, 2013). "Its increased expression, as observed in atopic dermatitis, led to decreased expression of an important epidermal barrier component, filaggrin, and increased expression of pro-inflammatory cytokines, including TNFα and CCL5." (PMID 24260356, 2013). "Keratinocytes are known to respond to various chemokines, such as chemokine (C-C motif) ligand (CCL)-17 (also known as TARC), CCL-22 (alternatively known as MDC), CCL-5 (synonym RANTES), and IL-8, which are involved in precipitating atopic dermatitis." (PMID 31208018, 2019). "In addition, the expression of IL-4, IL-13, CXCL10, CCL5, CCL17, and CCL22, which are atopic dermatitis mediators, increased 2- or 3-fold in HaCaT cells treated with DPM compared with that in the control group." (PMID 39599592, 2024). "In addition, the gene expression levels of IL-4, IL-13, CXCL10, CCL5, CCL17, and CCL22, which are related to atopic dermatitis, were significantly decreased by HCFE in DPM-stimulated HaCaT cells." (PMID 39599592, 2024). "Atopic dermatitis increased the expression levels of cytokines/chemokines, such as interleukin-5 (IL-5), macrophage inflammatory protein-1ß (MIP-1ß), MIP-2, chemokine (C-C motif) ligand 5 (CCL5), and IL-17, in BALB/c mouse." (PMID 30459600, 2018). "Similarly, CCR4-involving cell-cell communication, with the ligands CCL5, CCL17, CCL22, also showed diseased organ specificity, but in nonlesional atopic dermatitis and psoriatic skin." (PMID 40809141, 2024).
autoimmune disease (25 papers, 2005 to 2025). A disorder resulting from loss of function or tissue destruction of an organ or multiple organs, arising from humoral or cellular immune responses of the individual to their own tissue constituents. "Additionally, Zhernakova reported that several studies have shown that rs2107538, located in the first intron, can influence the transcriptional activity of CCL5, potentially contributing to susceptibility to autoimmune diseases." (PMID 40881695, 2025). "In addition to neoplastic diseases, CCL5 variants may be a positive factor in the course of other inflammatory and/or autoimmune diseases." (PMID 36983384, 2023). "FDOJ, on the other hand, is often associated with systemic diseases, such as inflammatory and neurodegenerative diseases of the central nervous system or autoimmune disorders, which are linked to high levels of CCL5/RANTES in the body." (PMID 40076479, 2025). "This previous study demonstrated that NK cells secrete various cytokines and chemokines such as IFN-γ, TNF-α and CCL5, contributing to the progression of autoimmune diseases by stimulating autoreactive T and B cells." (PMID 41343465, 2025). "Emerging evidence suggests that the CCR5/CCL5 axis may play an important role in Tregs trafficking to inflammation sites in cancer, infections, and autoimmune diseases." (PMID 38937380, 2024). "Thus, CCL5-mediated signaling may represent a conserved mechanism across autoimmune diseases, highlighting its therapeutic potential." (PMID 41343465, 2025). "CCR5 and its ligands C‐C motif ligand 3 (CCL3; also termed macrophage inflammatory protein [MIP]‐1α), CCL4 (MIP‐1β), CCL5 (regulated upon activation, normal T cell expressed and secreted [RANTES]), and CCL3L1 have been associated with exacerbation of chronic inflammatory and autoimmune diseases." (PMID 32525588, 2020). "Among them, TGFBR1, TGFBR2, CCL5, CD48, CD244A, and CD72 have been reported to be closely related to the pathophysiologic processes of autoimmune diseases." (PMID 35515003, 2022). "Although numerous studies indicated that CCL5 and CXCR4 played an important role in the progression of many diseases, including chronic liver disease, malignant tumor, and autoimmune disease, the specific mechanism needs to be further explored." (PMID 34484236, 2021). "In autoimmune diseases such as SLE, increased expression of chemokine receptors (CXCR2, CXCR3, CCR3 and CCR1) and elevated levels of chemokines such as MCP-1/CCL2, MIP-1/CCL-4, SDF-1/CXCL-12, RANTES/CCL5 and IP-10/CXCL-10 are observed." (PMID 36059466, 2022). "Met-CCL5 antagonizes CCR1 and CCR5 activation and function in response to their natural ligands CCL3-5, and this blockade is able to reduce inflammation in models of induced inflammatory and autoimmune diseases, but also after MI." (PMID 24512349, 2014).
coronary artery disease (25 papers, 2009 to 2025). "CCL-2 and CCL-5 (RANTES) are chemokines implicated in the pathophysiology of coronary artery disease." (PMID 37629526, 2023). "Case–control studies associated the CCL5 rs2107538 (403 C > T) with both increased risk of and protection against the development of coronary diseases." (PMID 29696014, 2018). "For instance, a polymorphism in the promoter region of the CCL5 gene called rs2107538 has been found associated with coronary artery disease." (PMID 22807925, 2012). "Frequencies of CCL5 alleles and allelic odds ratios (OR) and 95% confidence intervals (CI) for coronary artery disease in the CARDIoGRAM study." (PMID 22162987, 2011). "With elevated RANTES levels associated with high-risk groups in early plaque formation in patients with stable angina, recent studies on gene polymorphisms of the chemokine RANTES/CCL5 have shown their potential as predictive risk factors for coronary artery disease." (PMID 40218291, 2025). "In contrast, lower serum CCL5 was found to be associated with coronary heart disease." (PMID 26688689, 2015). "Therefore, our study was focused on the association between coronary artery disease with CCL5 A-403 and CCR5 59029A polymorphism." (PMID 26688689, 2015). "In humans, the gain-of-function polymorphism CCL5-G403A affects basal CCL5 expression levels and is associated with a higher risk of coronary artery disease (CAD), whereas the loss-of-function polymorphism CCR5Δ32 seems to be associated with a lower risk of myocardial infarction." (PMID 24741577, 2014). "Rothenbacher and colleagues demonstrated higher CXCL10 and CXCL8 and lower CCL5 levels in coronary heart disease patients compared with age- and gender-matched controls." (PMID 34835155, 2021). "We did not measure serum CCL5 levels in this study because the connection between serum CCL5 levels and the presence of coronary heart disease is controversial." (PMID 22292067, 2012). "Also in the CARDIoGRAM study (>22,000 cases, >60,000 controls), none of these CCL5 SNPs was significantly associated with coronary artery disease." (PMID 22162987, 2011). "Interestingly, most of these pro-inflammatory genes like CCL5, CXCL10, CXCL9, CTSK, and CD14 have been previously reported to be elevated in the serum of patients with coronary artery diseases." (PMID 35488341, 2022). "However, the association of the chemokine, CCL5, and its receptor, CCR5, polymorphism and coronary artery disease (CAD) in the Taiwanese has not been studied." (PMID 26688689, 2015). "However, the influence of CCL5 A-403 and CCR5 59029A polymorphism on coronary artery disease has not been identified in Taiwan's population." (PMID 26688689, 2015). "However, the absence of associations between (i) RANTES serum levels, (ii) CCL5 genotypes and (iii) RANTES content in carotid plaques and either coronary artery disease or incident coronary events in our cohorts suggests that RANTES may not be a novel coronary risk biomarker." (PMID 22162987, 2011).
eosinophilia (25 papers, 2005 to 2025). "CCL5 regulates a variety of immune cells, including the transport of T cells, monocytes, eosinophilia, etc., which can bind to at least four receptors, including CCR1, CCR3, CCR5 and GPR75, among which CCR5 is the main receptor of CCL5 in adipose tissue." (PMID 40725440, 2025). "One study showed that early phase steroid-induced resolution involves inhibition of eosinophilia in total nasal tissue and lamina propria and CCL5-dependent recruitment of cells in the nasal mucosa in AR." (PMID 35725523, 2022). "Reduced CCL5 production by cigarette smoke would be expected to limit eosinophilia and lymphocyte recruitment." (PMID 22808255, 2012). "Since no major CCL11 or IL-5 signature was observed in TIV-vaccinated NC99-challenged mice, we may be observing CCL5-mediated recruitment of eosinophils instead of canonical Type 2 cytokine-driven eosinophilia." (PMID 37600776, 2023). "The same treatment also significantly reduced the expression of genes linked to Th2 response and eosinophilia (Il4 and Il5 but not Il13) as well as eosinophil recruitment (Ccl5 and Ccl11) in Atg7fl/fl;Lyz2‐Cre ECRS mice." (PMID 35988262, 2022). "Interestingly, it has been demonstrated in an animal model of peritoneal dialysis that peritoneal eosinophilia and CCL5 elevation was particularly pronounced after exposure to dialysis fluids regarded as less biocompatible." (PMID 24523572, 2014). "The present demonstration of a reduced expression of CCL5, occurring simultaneously to the reduced tissue eosinophilia, suggests that CCL5, with its proposed roles in eosinophil and lymphocyte recruitment, can be of special importance as pharmacological target." (PMID 20459697, 2010). "In fibrosing alveolitis, macrophages (CD68+) and eosinophils are key sources of CCL5, with CCL5 correlating with eosinophil numbers in pulmonary fibrosis caused by sulfur mustard gas inhalation, suggesting a potential role of CCL5 in acting on CCR3 and contributing to eosinophilia during fibrosis." (PMID 39768150, 2024). "However, eosinophilia has been correlated with poor outcomes in mouse and human cryptococcosis, and in the presence of IM in our model, we observed an upregulation of pulmonary IL-5 and RANTES/CCL5, cytokines that play important roles in eosinophil maturation and trafficking." (PMID 30897162, 2019). "After demonstrating MBP, CCL5 and CCL11 in tissues of affected organs and presence of eosinophilia, we next evaluated levels of these and other eosinophilic granules and chemokines in sera." (PMID 28489854, 2017). "In addition, stimulated patients' PBMCs released increased levels of C-C-motif chemokine ligand 5 (CCL5), a potent chemotactic agent for eosinophils, which likely explains the observed eosinophilia." (PMID 31456795, 2019). "Furthermore, the levels of RANTES (CCL5) (a major eosinophil chemoattractant), IL-5 (known to regulate eosinophil differentiation and survival), and IL-33 (known to further contribute to exacerbated eosinophil) were all increased and coordinate with the increased amount of eosinophilia." (PMID 24876675, 2014). "We have focused on epithelial and subepithelial eosinophilia, expression of CCL11 and CCL5, and occurrence of apoptotic and non-apoptotic eosinophils in the human nasal mucosa with resolving tissue eosinophilia." (PMID 20459697, 2010). "We further demonstrate a degree of selectivity in the steroid action in that tissue CCL5 expression, but not CCL11, is reduced by budesonide along with its attenuating effects on tissue eosinophilia." (PMID 20459697, 2010). "It is worth noticing that despite the baseline eosinophilia, eosinophil chemo-attractants CCL11 and CCL5 did not correlate with eosinophil count and their concentration was either unaltered (CCL11) or decreased (CCL5) in S. stercoralis-infected subjects." (PMID 33059754, 2020).
Alzheimer disease (24 papers, 2014 to 2025). A progressive, neurodegenerative disease characterized by loss of function and death of nerve cells in several areas of the brain leading to loss of cognitive function such as memory and language. "Higher levels of CCL5 have been associated with Alzheimer’s disease (AD) in patients and the ApoE genotype; however, the link to pathology and plasticity has been little studied." (PMID 33931731, 2021). "For example, TGFβ1 inhibits microglia chemotaxis towards amyloid beta aggregates observed in Alzheimer’s disease via activation of TGFβR/SMAD-2-mediated downregulation of the chemokine CCL5." (PMID 30940161, 2019). "Similar CCL5 downregulation has also been observed in patients with Alzheimer’s disease." (PMID 40563378, 2025). "However, CCR5 and CCL5 have been studied in relation to the pathophysiology of other age-related neurodegenerative diseases such as Parkinson's and Alzheimer's disease." (PMID 38165703, 2024). "RANTES (CCL5), an endogenous ligand of CCR1, has pro-inflammatory effects in animal models of cerebral ischemia, Alzheimer’s disease, and autoimmune encephalomyelitis (EAE)." (PMID 35062973, 2022).